TEX30 (testis expressed 30)
Synonyms: C13orf27
Tractability: PROTAC: ubiquitination databases record sites on it.
Gene: Protein-coding gene on chromosome 13 (102,765,888 to 102,773,811, reverse strand). Ensembl gene ENSG00000151287.
Genetic constraint (gnomAD): Loss-of-function variants: 10 observed, 14.9 expected, observed/expected ratio (o/e) 0.67, 90% interval 0.41 to 1.14. The upper end of that interval is the gene's LOEUF score, 1.14, which puts it in group 4 of 6, group 1 being the genes least tolerant of losing a copy. Missense variants: 207 observed, 237.83 expected, observed/expected ratio (o/e) 0.87, 90% interval 0.78 to 0.98. Synonymous variants: 67 observed, 80.16 expected, observed/expected ratio (o/e) 0.84, 90% interval 0.69 to 1.02.
Homologues: Orthologues: chimpanzee TEX30 (100% identical), macaque TEX30 (97% identical), pig TEX30 (97% identical), rat Tex30 (96% identical), guinea pig TEX30 (95% identical), mouse Tex30 (95% identical), rabbit TEX30 (95% identical). Paralogues in human: KANSL3 (25% identical).
Diseases named in the same sentence as TEX30 in open-access papers:
TEX30 is named in the same sentence as 4 diseases in open-access papers, as found by Europe PMC text mining. Sharing a sentence is not in itself a finding about the gene and the disease.
TEX30 shares sentences with these, for which no sentence is quoted: carcinoma (1 paper); rectal adenoma (1); rectal cancer (1); rectal tumor (1).